ACP5 (acid phosphatase 5, tartrate resistant)
Description:
Involved in osteopontin/bone sialoprotein dephosphorylation. Its expression seems to increase in certain pathological states such as Gaucher and Hodgkin diseases, the hairy cell, the B-cell, and the T-cell leukemias.
Synonyms: TrATPase; TRAP; HPAP; TRAcP; TRACP5a; TRACP5b
Tractability: Antibody: UniProt predicts a signal peptide or a membrane-spanning region. PROTAC: ubiquitination databases record sites on it; its protein half-life has been measured.
Gene: Protein-coding gene on chromosome 19 (11,574,653 to 11,579,993, reverse strand). Ensembl gene ENSG00000102575.
Subcellular location: Lysosome
Subcellular location (Human Protein Atlas): Cytosol
Pathways (Reactome):
Metabolism: Vitamin B2 (riboflavin) metabolism
Gene Ontology:
Molecular function: acid phosphatase activity; ferric iron binding; ferrous iron binding; hydrolase activity
Biological process: bone resorption
Cellular component: cytosol; membrane; lysosome
Genetic constraint (gnomAD): Loss-of-function variants: 25 observed, 30.62 expected, observed/expected ratio (o/e) 0.82, 90% interval 0.59 to 1.14. The upper end of that interval is the gene's LOEUF score, 1.14, which puts it in group 4 of 6, group 1 being the genes least tolerant of losing a copy. Missense variants: 354 observed, 437.77 expected, observed/expected ratio (o/e) 0.81, 90% interval 0.74 to 0.88. Synonymous variants: 154 observed, 185.5 expected, observed/expected ratio (o/e) 0.83, 90% interval 0.73 to 0.95.
Homologues: Orthologues: chimpanzee ACP5 (99% identical), macaque ACP5 (98% identical), dog ACP5 (90% identical), guinea pig ACP5 (87% identical), rat Acp5 (86% identical), mouse Acp5 (85% identical), pig ACP5 (85% identical), zebrafish acp5a (56% identical), tropical clawed frog acp5 (56% identical), Caenorhabditis elegans F02E9.7 (37% identical).
Diseases named in the same sentence as ACP5 in open-access papers:
ACP5 is named in the same sentence as 146 diseases in open-access papers, as found by Europe PMC text mining. Sharing a sentence is not in itself a finding about the gene and the disease. The quoted sentences say what the papers report.
osteoporosis (68 papers, 2008 to 2026). A condition of reduced bone mass, with decreased cortical thickness and a decrease in the number and size of the trabeculae of cancellous bone (but normal chemical composition), resulting in increased fracture incidence. "The mechanisms of inhibition were via suppression of osteoporosis-related protein expression (NFATc1 and c-Fos), gene expression (Nfatc1, Ca2, Acp5, mmp9, CtsK, Oscar, and Atp6v0d2), and inhibited bone loss induced in the OVX model." (PMID 33859705, 2021). "ACP5 has been recommended as a serum marker for bone resorptive activity in pathological states, such as osteoporosis and notably, bone metastasis of cancers." (PMID 33795653, 2021). "ACP5 levels were significantly decreased in cultured GD macrophages after differentiation for 12 days, except for one macrophage cell line derived from GD patients with osteoporosis (P7)." (PMID 38667330, 2024). "The transcript levels of UBAP2 were significantly downregulated, while those of ACP5 and CTSK were upregulated in bone marrow samples from patients with osteoporosis compared with those in controls." (PMID 37339951, 2023). "Because UBAP2 mRNA expression was correlated with the osteoclastogenesis-related genes ACP5 and CTSK in the bone marrow samples of patients with osteoporosis, we further investigated to identify the UBAP2 associated molecule(s) involved in osteoclast differentiation." (PMID 37339951, 2023). "Expression levels of ALPL, BGLAP, and TNF were not significantly different between control and osteoporosis groups, but those of ACP5 and CTSK were significantly increased in patients with osteoporosis compared to those in the controls." (PMID 37339951, 2023). "Moreover, expressions of genes involved in osteoclast differentiation, TNF, ACP5, and CTSK, were all increased in the osteoporosis group compared to those in the normal control group." (PMID 37339951, 2023). "In addition, the expression levels of TRAP (ACP5) and RANK, expressed by osteoclasts, were unchanged or reduced, respectively, in these patients compared to those without osteopenia/osteoporosis." (PMID 33953168, 2021).
Spondyloenchondrodysplasia (22 papers, 2012 to 2026). "Spondyloenchondrodysplasia with immune dysregulation (SPENCDI) is autosomal recessive hereditary disease caused by tartrate resistant acid phosphatase 5 (ACP5) mutations." (PMID 40786056, 2025). "Case No. 9, who experienced an intracranial hemorrhage, was found to have a biallelic pathogenic ACP5 mutation, indicative of spondyloenchondrodysplasia (SPENCD) upon further genetic testing." (PMID 40941697, 2025). "Spondyloenchondrodysplasia (SPENCD) is a rare immuno-osseus disease due to biallelic mutations in ACP5, resulting in a loss of tartrate-resistant acid phosphatase (TRAP) activity and enhanced type I interferon signalling." (PMID 41049574, 2025). "Spondyloenchondrodysplasia with immune dysregulation (SPENCDI) is defined as an autosomal recessive genetic disorder caused by ACP5 gene mutation, which mainly affects the skeletal and the immunologic systems' function, along with neurological impairment." (PMID 38883133, 2024). "Spondyloenchondrodysplasia (SPENCD) caused by biallelic mutations of ACP5 is a rare skeletal dysplasia characterized with neurological impairment and immune dysfunction." (PMID 40625455, 2024). "LoF variants in ACP5 have been associated with Spondyloenchondrodysplasia (SPENCD), a rare skeletal disorder that often presents with lupus-like characteristics." (PMID 38420886, 2024). "Interestingly, the patient (D.II.1) who carried the A536T variant that retained normal suppressive function was also compound heterozygous for ACP5, which is a known cause of spondyloenchondrodysplasia with immune dysregulation that shares features with SLE." (PMID 38417019, 2024). "The clinical manifestations of spondyloenchondrodysplasia with immune dysregulation (SPENCDI) associated with ACP5 mutations are similar to those of AGS in terms of neurological manifestations (spasticity, intracranial calcifications) as well as manifestations of autoimmunity (mimicking SLE)." (PMID 38914753, 2024). "Diseases associated with ACP5 include spondyloenchondrodysplasia with immune dysregulation." (PMID 35401685, 2022). "Spondyloenchondrodysplasia with immune dysregulation (SPENCDI) is a rare autosomal recessive genetic disorder caused by a homozygous mutation of the ACP5 gene." (PMID 38883133, 2024). "Biallelic mutations in the ACP5 gene cause spondyloenchondrodysplasia with immune dysregulation (SPENCDI)." (PMID 38347954, 2024). "Spondyloenchondrodysplasia (SPENCD) is an immune-osseous disorder caused by biallelic variants in ACP5 gene and is less commonly associated with neurological abnormalities such as global developmental delay, spasticity and seizures." (PMID 37010587, 2023). "Loss-of- function variants in ACP5 has been identified as a cause of spondyloenchondrodysplasia with immune dysregulation (SPENCDI, MIM: 607944), a rare autosomal recessive syndrome characterized by skeletal and immune abnormalities." (PMID 35126383, 2021). "Another disease that is usually associated with autoimmune SLE is spondyloenchondrodysplasia (SPENCD), a rare autosomal recessive skeletal dysplasia caused by mutations in the ACP5 (acid phosphatase 5) gene." (PMID 37189745, 2023). "Another rare condition is the spondyloenchondrodysplasia with immune dysregulation (SPENCD), a skeletal dysplasia, neurological disease and immune dysregulation, caused by a autosomal recessive mutation in the tartrate-resistant acid phosphatase (TRAP) gene (ACP5 gene)." (PMID 36569887, 2022). "Biallelic mutations in ACP5, encoding tartrate-resistant acid phosphatase (TRACP), have recently been identified to cause the inherited immuno-osseous disorder, spondyloenchondrodysplasia (SPENCD)." (PMID 32214327, 2020). "Spondyloenchondrodysplasia (SPENCD) is an autosomal recessive skeletal dysplasia caused by loss of function mutations in acid phosphatase 5, tartrate resistant (ACP5)." (PMID 28740483, 2017).
Spondyloenchondrodysplasia (continued). "ACP5 is another gene, encoding tartrate-resistant acid phosphatase (TRAP), that has been associated to an immuno-osseous disease: the spondyloenchondrodysplasia (SPENCD)." (PMID 22883345, 2012).
periodontitis (15 papers, 2015 to 2026). An acute or chronic inflammatory process that affects the tissues that surround and support the teeth. "Relative mRNA expression levels of PI3K, Acp5, and NFATc1 in the normal human periodontal ligament and chronic periodontitis were analyzed by quantitative reverse-transcription polymerase chain reaction." (PMID 36979821, 2023). "The expression of PI3K (P = 0.009), Acp5 (P < 0.001) and NFATc1 (P = 0.003) genes were all higher in the chronic apical periodontitis samples than in healthy periodontal ligament tissue, and the difference was statistically significant." (PMID 35953782, 2022). "The expression of PI3K, Acp5 and NFATc1 genes in chronic apical periodontitis sample groups was significantly increased relative to healthy periodontal ligament tissue (P < 0.05)." (PMID 35953782, 2022). "The relative mRNA expression of PI3K, Acp5 and NFATc1 in the normal human periodontal ligament and in chronic apical periodontitis were analyzed by real-time quantitative polymerase chain reaction (RT-qPCR)." (PMID 35953782, 2022). "On the other hand, ACP5 expression was significantly upregulated in the groups that received ligature alone (periodontitis) or ligature and control-siRNA/C12-GD-Spe treatment (periodontitis + placebo injection) compared to the baseline control group (no periodontitis)." (PMID 38920924, 2024).
breast carcinoma (11 papers, 2010 to 2025). "ACP5 encodes a metalloprotein enzyme that belongs to the acid phosphatase family, up-regulated in breast cancer and LUAD, associated with poor outcomes." (PMID 34595103, 2021). "Additionally, ACP5, which encodes a metalloprotein enzyme, has been reported to promote tumor metastasis and recurrence in many cancers, like hepatocellular carcinoma and breast cancer." (PMID 34568059, 2021). "Studies have shown that ACP5 is closely related to the cell invasion, disease progression and distant metastasis of many tumors, such as melanoma and breast cancer." (PMID 33753989, 2021).
lupus (10 papers, 2014 to 2024). "Recently, a significant number of genes have been implicated in monogenic lupus, such as several complement deficiencies, ACP5, DNASE1, DNASE1L3, PRKCD, RAG2 genes, etc.." (PMID 34796153, 2021). "Several different biallelic null mutations in ACP5 distributed throughout the protein have been identified in individuals diagnosed with SPENCD-associated lupus." (PMID 30459768, 2018). "We and others have shown earlier that mutations of ACP5 can cause autoimmune cytopenia, immuno-osseous dysplasia, spasticity with leukodystrophy, systemic lupus erythematosus (SLE), Moyamoya syndrome and Sjogren’s syndrome." (PMID 32214327, 2020). "For instance, we know about the existence of cases of systemic lupus erythematosus caused by monogenic mutations in the C1qA, B, C, C1R, DNASE1, DNASE1L3, and ACP5 genes, among many other predisposing genetic variations." (PMID 36900420, 2023). "Some single gene variants (SAMHD1, RNASEH2ABC, ADAR1, IFIH1, ISG15, ACP5, TMEM173) can cause monogenic lupus." (PMID 35783307, 2022). "Although loss-of-function mutations of Acp5 cause spondyloenchon-drodysplasia with immune dysregulation (SPENCDI), which is a skeletal and neurological disorder with lupus-like symptoms and a type I interferon signature, the expression of Acp5 mRNA increased in patrolling monocytes in NZBWF1 mice." (PMID 34868046, 2021).
Arthritis (8 papers, 2018 to 2026). Inflammation of a joint. "Casp3, a core enzyme in the apoptosis signaling pathway, plays a crucial role in arthritis development through apoptosis induced by its activation, Acp5, highly expressed in osteoclasts, participates in bone matrix demineralization and degradation." (PMID 41508102, 2026).
osteopetrosis (7 papers, 2013 to 2024). Osteopetrosis, also known as marble bone disease, is a descriptive term that refers to a group of rare, heritable disorders of the skeleton characterized by increased bone density on radiographs. "Acp5-deficient mice were reported to show mild osteopetrosis." (PMID 24223830, 2013).
rheumatoid arthritis (7 papers, 2017 to 2024). A chronic, systemic autoimmune disorder characterized by inflammation in the synovial membranes and articular surfaces. "Acp5 and Ctsk have been identified as markers for Rheumatoid Arthritis and are upregulated in the synovial tissue." (PMID 39600948, 2024).
lung carcinoma (6 papers, 2021 to 2025). "A study showed that silencing RUNX1 inhibits lung cancer progression via the ERK/MAPK axis by modulating ACP5 expression." (PMID 39201328, 2024). "In lung cancer, profiling-2 and ACP5 regulate Smad2 and Smad3 expression for lung cancer growth and metastasis, and miR-15a and miR-32-5p directly regulate SMAD3 expression for lung cancer metastasis." (PMID 37121971, 2023).
osteosarcoma (5 papers, 2013 to 2024). A usually aggressive malignant bone-forming mesenchymal neoplasm, predominantly affecting adolescents and young adults. "GSEA conducted on all genes demonstrated that patients of S-I tended to exhibit more osteoclastic bone resorption (e.g., ACP5, SIGLEC15, CTSK), which was consistent with the clinical manifestations of osteosarcoma at the early stage." (PMID 36874110, 2023).
atherosclerosis (4 papers, 2019 to 2023). A disease characterized by the build-up of fatty material and calcium deposition in the arterial wall resulting in partial or complete occlusion of the arterial lumen. "The present study demonstrated that lncRNA-H19 promoting ACP5 protein expression contributed to atherosclerosis and increases the risk of ischemic stroke." (PMID 30778327, 2019). "Therefore, we speculate that ACP5 may cause atherosclerosis by affecting the proliferation and apoptosis of endothelial vascular cells." (PMID 30778327, 2019). "lncRNA-H19 induced the occurrence of atherosclerosis through positive regulation of ACP5 protein, leading to the emergence of ischemic stroke." (PMID 30778327, 2019). "In our present study, we screened atherosclerosis-related gene lncRNA-H19 and its target gene ACP5 by using bioinformatics technique." (PMID 30778327, 2019). "Finally, ACP5, MRAP2, and MME were found to show associations with both atherosclerosis and lncRNA-H19." (PMID 30778327, 2019). "The experiments demonstrated that lentivirus-mediated stromal cell-derived factor-1 (SDF-1)-forced expression upregulated the level of ACP5, promoted the proliferation, and inhibited the apoptosis of arterial intimal cells, revealing lncRNA-H19-mediated atherosclerosis." (PMID 30778327, 2019).
Autoimmunity (4 papers, 2015 to 2025). The occurrence of an immune reaction against the organism's own cells or tissues. "Among other examples, deficiency in Acp5 (encoding TRAcP) induces bone dysplasia but also autoimmunity and deletion or inhibition of Ctsk blocks both bone degradation and inflammation." (PMID 31275328, 2019). "We report on a child, who presented with spasticity, multisystem inflammation, autoimmunity and immunodeficiency with minimal metaphyseal changes due to compound heterozygosity for two novel ACP5 mutations." (PMID 26346816, 2015). "Notably, Acp5-null mice have not been described to manifest overt autoimmunity, which is such a prominent feature of ACP5-related disease in humans." (PMID 41049574, 2025).
melanoma (4 papers, 2014 to 2021). A malignant, usually aggressive tumor composed of atypical, neoplastic melanocytes. "Functional genomics have implicated ACP5 as one among six genes with verified oncogenic and pro-invasive capability in human malignant melanoma." (PMID 32214327, 2020). "Genes encoding acid phosphatase 5 (ACP5), a transport protein recently recognized as a prognostic biomarker in primary melanomas, and T-box 2 (TBX2), a transcription factor that is crucial in embryonic development and in suppressing senescence in melanoma, were also up-regulated in melanospheres." (PMID 24733089, 2014).
prostate carcinoma (4 papers, 2013 to 2024). A carcinoma that arises from epithelial cells of the prostate gland. "In order to characterize ongoing bone cell activity in clinical cases of prostate cancer bone metastasis, we selected a set of genes to represent osteoclast activity (ACP5, CTSK, MMP9), osteoblast activity (ALPL, BGLAP, RUNX2) and osteocytes (SOST)." (PMID 29670000, 2018).
ischemic stroke (3 papers, 2019 to 2024). A stroke disorder caused by obstruction of blood flow to the brain, due to thrombotic (local blood clot formation) or embolic (due to a blood clot or other material traveling from another site) event. "In the pathogenesis of ischemic stroke, lncRNA H19 regulates ACP5 expression by interaction with ACP5." (PMID 39766887, 2024). "In patients who had suffered an ischemic stroke and had large artery atherosclerosis, the levels of both lncRNA-H19 and ACP5 were significantly increased compared to patients who had suffered an ischemic stroke and had a different stroke etiology." (PMID 38927529, 2024).
Obesity (3 papers, 2018 to 2025). Accumulation of substantial excess body fat. "Interestingly, all tissues of T2D patients showed altered expression of genes involved in the inflammation response—such as SOCS1 in WB; CCL20 and SLAMF1 in SAT; ACP5, FOS, and JUN in VAT; and PLA2G2A in LT, showing the relevance of the systemic chronic inflammation in obesity and T2D." (PMID 29466957, 2018).
psoriasis (3 papers, 2016 to 2021). An autoimmune condition characterized by red, well-delineated plaques with silvery scales that are usually on the extensor surfaces and scalp. "Most parents heterozygous for an ACP5 mutation in our cohort appear healthy; however, two parents had short stature, two had a history of neuropsychiatric illness, and one psoriasis." (PMID 26951490, 2016).
chordoma (2 papers, 2024). Chordomas are rare malignant tumors arising from embryonic remnants of the notochord in axial skeleton. "Recently, a study revisited the chordoma bone-destructive invasive fronts to find cells expressing brachyury, tartrate-resistant acid phosphatase (TRAP/ACP5), and cathepsin K (CatK/CTSK), similarly to osteoclasts in bone resorption capacities." (PMID 39684443, 2024).
hepatocellular carcinoma (2 papers, 2019 to 2021). A malignant tumor that arises from hepatocytes. "Elevated expression of ACP5 in hepatocellular carcinoma (HCC) tissues was found to be associated with microvascular infiltration, poor differentiation, high lymph node metastasis, and poor survival." (PMID 30778327, 2019).
Immunodeficiency (2 papers, 2015 to 2016). Failure of the immune system to protect the body adequately from infection, due to the absence or insufficiency of some component process or substance. "Recurrent bacterial and viral infections were reported in five patients, raising the suggestion that immunodeficiency is a part of ACP5-associated disease." (PMID 26951490, 2016).
Metaphyseal dysplasia (2 papers, 2015 to 2023). The presence of dysplastic regions in metaphyseal regions. "Medical studies have found that mutations in ACP5 can cause metaphyseal dysplasia, autoimmune regulation disorders and nerve damage." (PMID 37259472, 2023).
Cardiomyopathies (1 paper, 2025). "These disorders are categorized into major clinical groups, such as Skeletal Dysplasias (e.g., analysis of genes like ACAN, ACP5, and ACVR1), Osteogenesis Imperfecta (COL1A1, COL1A2, BMP1), Metabolic Disorders (ACE, AGT, BICC1), and Cardiomyopathies, among others." (PMID 40282387, 2025).